PINK1 (PTEN induced kinase 1)
Diseases named in the same sentence as PINK1 in open-access papers (continued):
Sharing a sentence is not in itself a finding about the gene and the disease.
kidney (3 papers, 2021 to 2022). "In the current study, we detected the induction of PINK1-Parkin mediated mitophagy in both in vitro and in vivo models of lung IR injury." (PMID 34602075, 2021). "As SIRT1 acts upstream of PINK1, we also explored mechanisms underlying the effects of APN on upregulating mitophagy under diabetic lung IR conditions." (PMID 34602075, 2021). "Conversely, knockout of PTEN-induced kinase 1 (PINK1), parkin RBR E3 ubiquitin protein ligase (PARK2), or BCL2-interacting protein 3 (BNIP3) inhibited mitophagy in TECs, which aggravated kidney injury." (PMID 35501332, 2022). "Third, we found evidence that, by upregulating SIRT1- PINK1-dependent mitophagy, APN might ameliorate mitochondrial dysfunction, thus reducing ROS production and inflammation, contributing to cell survival and ultimately preserving lung function during diabetic lung IR injury." (PMID 34602075, 2021).
immune disorders (2 papers, 2018 to 2022). "PINK1 and BMSCs can synergistically regulate and alleviate immune disorders in kidneys with IRI-AKI and enhance the anti-inflammatory and immunosuppressive properties of BMSCs, thus promoting the repair of kidneys with IRI-AKI." (PMID 35962179, 2022). "While in the past few years, it has been shown that PINK1 and Parkin-related immune system disorders are indeed responsible for the upstream mechanism of mitochondrial aberrations." (PMID 30319601, 2018).
inflammation (2 papers, 2023 to 2024). Aberrant reaction of the microcirculation characterized by movement of fluid and leukocytes from the blood into extravascular tissues. "Moreover, macrophage-derived exosomes containing the lncRNA MSTRG.91634.7 target PTEN-induced putative kinase 1 (PINK1) to inhibit fibroblast activation, thereby limiting silica-induced lung inflammation and fibrosis in mice." (PMID 38655063, 2024).
neurodevelopmental disorder (1 paper, 2020). A behavioral and cognitive disorder with onset during the developmental period that involves impaired or aberrant development of intellectual, motor, or social functions. "PARK2 and PINK1 are the main regulators of the MQC, and thus could play a functional role in psychiatric and neurodevelopmental disorders like subgroups of patients with ADHD." (PMID 33353000, 2020).
PINK1 also shares sentences with these, for which no sentence is quoted: frontotemporal dementia (4 papers); multiple sclerosis (4); Ataxia (3); Crohn disease (3); multiple myeloma (3); acute lung injury (2); acute myeloid leukemia (2); blood cancer (2); brain cancer (2); cerebral infarction (2); chronic heart failure (2); Clear Cell Renal Cell Carcinoma (2); intestinal bacterial infection (2); Leigh syndrome (2); memory impairment (2); neuropathy (2); neurotoxicity (2); schizophrenia (2); scrapie (2); skin cutaneous melanoma (2); adenoma (1); adrenal hypoplasia congenita (1); adrenal tumors (1); age-related macular degeneration (1); alcoholic fatty liver disease (1); amyloid (1); Anorexia (1); autonomic dysfunction (1); autosomal recessive disease (1); autosomal recessive primary microcephaly (1).
A further 88 diseases each share a sentence with PINK1 in 1 paper.